INS (insulin)
Diseases named in the same sentence as INS in open-access papers (continued):
Sharing a sentence is not in itself a finding about the gene and the disease.
diabetes (continued). "Another clinical study indicated that patients with a high serum level of insulin Ab have a longer duration of diabetes, a higher level of BMI, and a lower level of C-peptide." (PMID 36589820, 2022). "He developed severe rebound euglycemic diabetic ketoacidosis due to the continuous usage of empagliflozin for glycemic control alongside intravenous insulin." (PMID 34983625, 2022). "It is interesting to note that the link between GSK3 and T2D diabetes has been initially established through its role in the insulin signaling pathway." (PMID 36499613, 2022). "Diabetes mellitus is a chronic condition that occurs when blood glucose levels increase because the body cannot produce enough insulin or cannot effectively use the insulin it produces." (PMID 35741413, 2022). "Algorithms based on fuzzy logic are less common, and modulate insulin delivery according to a set of rules designed to imitate the knowledge and reasoning of experienced diabetes clinicians." (PMID 35733769, 2022). "Linear regression was used to examine the associations of dietary antioxidant micronutrients with HbA1c and estimated insulin sensitivity (eIS) in models adjusted for relevant covariates and stratified by diabetes status." (PMID 35789593, 2022). "This study aimed to evaluate the efficacy of hypoxia-persistent insulin-producing cells (IPCs) against diabetes in vivo." (PMID 36248064, 2022). "Elevated blood free fatty acids (FFAs), as seen in obesity, impair insulin action leading to insulin resistance and Type 2 diabetes mellitus." (PMID 35011728, 2022). "Despite recent advances in the management of diabetes and the rise of new technologies for insulin administration, lipodystrophy still represents a troublesome complication for children and adolescents suffering from T1D." (PMID 35884071, 2022). "For late pregnancy, proper weight gain during pregnancy, management of pregnancy complications (diabetes, hypothyroidism, etc.)and intensive insulin treatment should also be emphasized." (PMID 36405614, 2022). "PTP1B is widely expressed in insulin sensitive tissues and in tissues that are affected by diabetes complications." (PMID 36012215, 2022). "T2DM is the most common form of diabetes, accounting for 90–95% of DM cases, and is characterized by insulin resistance and abnormal insulin secretion." (PMID 36080485, 2022). "It has long been known that chronic hyperglycaemia per se has deleterious effects on various tissues, resulting in further deterioration of insulin sensitivity, impaired insulin secretion, and the development of overt diabetes." (PMID 36058931, 2022). "Being able to recognise the symptoms of high‐ or low‐blood glucose levels can support one's ability to manage diabetes with insulin." (PMID 35983585, 2022). "In clinical trials in participants with diabetes, saroglitazar has demonstrated beneficial effects on atherogenic dyslipidemia and insulin sensitivity." (PMID 35457120, 2022). "A randomized control trial comparing family-directed versus individual diabetes interventions found improved blood glucose levels, insulin sensitivity, and lipid profiles among the family-directed group." (PMID 36141824, 2022). "In this work, AKT was significantly activated after phycocyanin treatment in T2DM mice and insulin-resistant SMMC-7721 cell models, which provided the underlying mechanism of phycocyanin in the process of ameliorating diabetes." (PMID 37430932, 2022). "In the next section, we focus on insulin secretion from pancreatic beta cells, insulin resistance, and the functioning of skeletal muscle UCPs in mouse models of obesity and diabetes." (PMID 35323702, 2022). "So, according to a forum for injection technique held in Malaysia, all persons with diabetes who are prescribed insulin treatment should be educated about the symptoms and early management of hypoglycemia." (PMID 35854336, 2022).
diabetes (continued). "In this study, we successfully developed a differentiation and transplantation technology of insulin-secreting cells for the fundamental treatment of diabetes." (PMID 35214135, 2022). "Analyzing the choice of hypoglycemic agents among each cluster, the choice of insulin in each cluster generally increased with the prolongation of diabetes duration." (PMID 36457559, 2022). "Piperidine alkaloids manage diabetes mellitus by increasing basal glucose absorption, lowering blood glucose levels, potentiating pancreatic insulin production, and activating AMPK and PPAR-γ, thereby controlling T2D." (PMID 36144587, 2022). "In animal models of diabetes, administration of astaxanthin improved insulin resistance and insulin secretion, reduced hyperglycemia, and attenuated retinopathy, nephropathy, and neuropathy." (PMID 35893262, 2022). "The diabetic rats were randomly divided into diabetes mellitus group (DM group), insulin treatment group (DM + INS group) and melatonin treatment group (DM + MT group)." (PMID 35962432, 2022). "These two hormones inhibit appetite, promote fat oxidation, promote insulin secretion and reduce glucagon, and inhibit hepatic steatosis and the development of diabetes." (PMID 36618372, 2022). "Bacterial biosynthesis of B2 and B9 were negatively associated with diabetes and its related parameters, including HOMA-IR, insulin level, glucose level, and diabetes." (PMID 36474346, 2022). "The A+B+C triple drug combination was superior to all the double drug combinations in preventing diabetes onset, and this was accompanied by significant increases in circulating levels of C-peptide and insulin." (PMID 36339443, 2022). "Technology to facilitate or inhibit diabetes management in people with intellectual disabilities using insulin, emerged briefly in the results." (PMID 35983585, 2022). "In patients with Type 1 diabetes mellitus, the pancreas is unable to secrete insulin, leading to the inability to convert glucose into energy." (PMID 35265101, 2022). "Diabetes mellitus (DM) is one of the most prevalent metabolic disorders resulting from chronic hyperglycaemia due to problems in insulin secretion, insulin action, or both." (PMID 36438767, 2022). "Whereas in diabetes, the enhancement of insulin strongly activates the PI3K-Akt (phosphatidylinositol 3‐kinase-protein kinase B) pathway that leads to a robust CD36 expression." (PMID 35396566, 2022). "This research aimed to explore the curative effect of short-term insulin pump in the treatment of type 2 diabetes mellitus (T2DM) patients with lower extremity arterial disease (LEAD) based on ultrasonography." (PMID 35669363, 2022). "The induction of diabetes with HFD/STZ caused a significant inhibition (p ≤ 0.05) of genes and proteins expression of all studied insulin-sensitizing signaling pathways; GLUT4, AMPK, and PI3K in skeletal muscle when compared to that of the control." (PMID 36364019, 2022). "Concerted studies of insulin and glucagon are necessary to understand the effects of dietary modifications on obesity and diabetes." (PMID 36056607, 2022). "Despite thiazolidinediones (TZDs), a class of PPARγ agonists, having been proven to be potent insulin sensitizers, their use is restricted in the treatment of diabetes for their adverse effects." (PMID 36551260, 2022). "Using isolated pancreatic β-cell lines such as MIN6 cells is a basic approach to initially investigate a protein or signaling pathway to understand its role in insulin dynamics and is used extensively in the field of diabetes research." (PMID 36030052, 2022). "Diabetes mellitus (DM) is characterized by elevated blood sugar levels (hyperglycemia) that are brought on by dysfunction in the production or action of insulin or both." (PMID 36431808, 2022).
diabetes (continued). "Hexamers are the storing conformations adopted by the hormone in pancreatic β cells, and they are the forms preferentially used in pharmaceutical formulations to avoid insulin-derived amyloidosis phenomena in diabetes mellitus patients." (PMID 35330199, 2022). "Another study reported that XA, which binds to insulin, and QA, which decreases proinsulin secretion and suppresses insulin release play a crucial role in the pathogenesis of diabetes." (PMID 34617264, 2022). "With feedback, rising blood glucose levels signal an overproduction of insulin in pancreatic cells (hyperinsulinemia), which can result in pancreatic dysfunction and consequently the development of diabetes." (PMID 35563135, 2022). "There is no cure for diabetes, but it can be treated and controlled, with treatment being divided into two kinds: subcutaneous insulin injection and oral hypoglycemic drugs." (PMID 36558993, 2022). "Continuously elevated insulin and glucose blood levels are hallmarks of type 2 diabetes and pre‐diabetes, and both CR and IF have been shown to reduce insulin levels." (PMID 34779138, 2022). "After the operation, 33 (47%) of the patients had a remission from diabetes, 5 patients (7%) needed only diet as their treatment, 21 patients (30%) needed oral medications, and 11 patients (16%) needed insulin (p < 0.001)." (PMID 36557274, 2022). "In dogs, PZI has been described for the management of diabetes mellitus and a licensed recombinant human insulin formulation is available for use in dogs containing 40 U/mL (Prozinc, Boehringer Ingelheim)." (PMID 35152907, 2022). "For example, 40% (n = 8) of the children with T1DM were considered to have poor diabetes control at the time of recruitment; 35% were on insulin pumps while the others were on insulin pens or multiple insulin injections per day." (PMID 35270604, 2022). "Family, support staff and healthcare professionals require information, education, and training to be confident and competent to facilitate diabetes management with insulin for people with intellectual disabilities." (PMID 35983585, 2022). "In animal models, the induction of Nrf2 prevents reactive species damage, improves insulin sensitivity, and protects from diabetes complications." (PMID 35740085, 2022). "Studies have shown that calcium channels on the islet β cell membrane regulated intracellular calcium signals, thereby affecting insulin secretion, which were closely related to the occurrence, development, and treatment of diabetes." (PMID 35601016, 2022). "PPAR-γ is a transcription factor regulating insulin sensitivity and adipogenesis, and agonistic drugs find applications in diabetes and lipid disorders." (PMID 35903083, 2022). "Induction of diabetes significantly reduced the levels of serum insulin, whereas metformin and AECPS administration increased it, with AECPS (16.8 mg/kg) comparing well with the normal controls." (PMID 35308202, 2022). "Because an increasing number of diabetes patients are using insulin pump technologies, it is of utmost importance that healthcare providers have the knowledge and means to care for these patients." (PMID 36107913, 2022). "The main objective was to address physician barriers toward insulin therapy so as to start tackling these barriers and improve the quality of care and decrease the burden of diabetes-related complications." (PMID 36554673, 2022). "Excessive accumulation of unfolded or misfolded proteins can cause ER stress, which triggers the death of pancreatic islet β-cells, insulin resistance in skeletal muscle and the liver, and diabetes." (PMID 36358477, 2022). "Guidelines recommend that insulin therapy should be initiated timely in patients with a long duration of diabetes, use of oral hypoglycaemic drugs that fail to achieve goals and poor islet function." (PMID 35574003, 2022).
diabetes (continued). "Diabetes is a long-term metabolic condition that results in high blood sugar levels from either reduced insulin production or diminished tissue sensitivity to insulin." (PMID 36249656, 2022). "The testing frequency of HbA1c and ACR, frequency of insulin prescription, and diabetes-related costs were significantly but minimally related to the occurrence of acute complications." (PMID 35330461, 2022). "The duration of diabetes mellitus, and the number of participants on insulin therapy were ignored since several of the original studies did not report those details." (PMID 36307791, 2022). "Women in the insulin group had a greater proportion of a family history of diabetes mellitus (59.1 vs. 39.8%, respectively, p = 0.019) and a personal history of GDM (31.8 vs. 14.5%, respectively, p = 0.011)." (PMID 35329840, 2022). "The expanded production of adipokines or cytokines, for example, tumor putrefaction factor, resistin, and retinol-restricting protein 4 have been proposed to connect stoutness with insulin obstruction, which advances to diabetes." (PMID 35268815, 2022). "Compared with patients of European descent, Asians with type 2 diabetes have more severe adiposity at the same level of BMI, develop diabetes at a younger age, and demonstrate impaired insulin secretion to compensate for insulin resistance." (PMID 35763031, 2022). "Type 1 Diabetes Mellitus (T1DM) is treated with insulin replacement therapy aiming to recreate the body’s normal fluctuations in secreting insulin." (PMID 36253850, 2022). "At least in the case of the sirtuins SIRT1, SIRT3, SIRT4, and SIRT6, much research has been performed on the regulation of insulin and glycaemic control, as well as the onset and management of diabetes mellitus." (PMID 36361416, 2022). "Insulin is the most common type of medication prescribed in type 1 diabetes mellitus treatment and can also be used in some type 2 diabetes mellitus cases." (PMID 36091798, 2022). "Diabetes mellitus is one of the most common chronic diseases in the world, characterized by pancreatic β-cell dysfunction and peripheral insulin resistance." (PMID 36615714, 2022). "Various categories of antidiabetic drugs available on the market for treatment and management of diabetes mellitus include insulin analogues, sulphonylureas, biguanides, dipeptidyl peptidase-4 inhibitors, thiazolidinediones and ⍺-glucosidase inhibitors." (PMID 36091798, 2022). "The participants had a mean age of 52 (SD 10.2) years, a median duration of diabetes of 11 years, and 81.9% (127/155) were on insulin therapy before hospital admission." (PMID 35881437, 2022). "The group with DF was also characterized by a longer duration of diabetes (p < 0.05) and a higher prevalence of patients treated with insulin (p < 0.001)." (PMID 36557068, 2022). "The ethyl acetate extract of leaves also showed notable antihyperglycemic action against streptozotocin-induced diabetic animal models (20 mg/kg b.w. dose) by enhancing insulin secretion of β-cells." (PMID 36557843, 2022). "retrospectively analyzed 37 pregnant women with insulin-managed diabetes during Ramadan (24 with T2DM, 13 with GDM) with mean gestational age 25 weeks." (PMID 35813638, 2022). "The wound healing rate was determined over a 28-day interval in healthy control (Control), control with diabetes (DControl), poloxamer treatment (Pox), and poloxamer plus insulin injection (Poxin) mice." (PMID 35311032, 2022). "Diabetes is treated with oral hypoglycemic drugs and insulin injection to reduce blood glucose levels, improve insulin secretion, and enhance insulin sensitivity." (PMID 35056765, 2022). "Type 1 diabetes mellitus is characterized by the autoimmune destruction of pancreatic beta cells, resulting in insufficient insulin production and the development of hyperglycemia." (PMID 36364951, 2022). "The endocrine organoids at the center of diabetes are the insulin-producing pancreatic islets of Langerhans." (PMID 35600597, 2022).
diabetes (continued). "For example, the insulin hexamer is commonly used as a long-acting insulin in the treatment of diabetes, however, the dissociation of the hexamer form into monomeric forms is a slow and difficult process." (PMID 36348051, 2022). "The relationship between obesity and diabetes is based on a progressive defect or decrease in insulin secretion, as well as an increased insulin resistance." (PMID 35804780, 2022). "Type 2 Diabetes Mellitus is one of the most common metabolic disorders, and is characterized by abnormal blood sugar level due to impaired insulin secretion or impaired insulin action—or both." (PMID 35956652, 2022). "This study is the first to explore the needs of individuals with T2D who are recommended or prescribed insulin therapy, via a thematic analysis of diabetes health forums." (PMID 36197724, 2022). "Diabetes mortality at ages younger than 25 years can serve as a readily available indicator for the surveillance of basic diabetes care and access to insulin around the world." (PMID 35143780, 2022). "The core problem of BGL-detection based on exhaled breath analysis is that the acetone level is influenced by many factors such as insulin injection, type of diabetes, alcohol intake, exercise, food and beverage intake, etc.." (PMID 35062385, 2022). "In the peripheral nervous system, activation of sirtuin 1 can improve insulin resistance, increase glucose sensing and insulin secretion and brain insulin resistance drives diabetes related cognitive decline by inhibiting sirtuin 1 signaling." (PMID 36012263, 2022). "Considering the total study cohort, 70 patients (35%) were diagnosed with diabetes prior to surgery, and 46 patients (23%) were insulin-dependent." (PMID 36615050, 2022). "Patients with diabetes were predominantly prescribed metformin, glibenclamide or insulin injections." (PMID 36028271, 2022). "Increased insulin resistance and impaired insulin secretion are significant characteristics manifested by patients with type 2 diabetes mellitus (T2DM)." (PMID 35432205, 2022). "It is known that the expression level of miR-125a-5p is reduced in diabetes and that miR-125b-5p upregulation enhances insulin sensitivity by pancreatic β-cell activation." (PMID 34974535, 2022). "It is incumbent upon all physicians to identify safe and effective insulin dosing recommendations during Ramadan for Muslims, a cohort claiming almost one-third of all persons with diabetes worldwide." (PMID 35634376, 2022). "Diabetes is characterized by dysfunction and/or death of insulin-producing islet β cells, leading to hyperglycemia." (PMID 35448531, 2022). "Although understanding the mechanisms by which insulin suppresses adipocyte lipolysis is critical to develop potential therapeutic strategies to mitigate IR and diabetes mellitus, the detailed mechanisms remain controversial and incomplete." (PMID 35283787, 2022). "The rationale for this selection is the fact that endometrial cancer has been strongly correlated with obesity and diabetes and, furthermore, seems to be affected by circulating insulin/IGF1 levels." (PMID 35626664, 2022). "Insulin pump therapy seemed to achieve a lower HbA1c level among those diagnosed at the age of 10-19 years or with ≥5 years of duration of diabetes." (PMID 35757419, 2022). "A 42‐year‐old pregnant lady with pre‐existing diabetes was treated with insulin during first trimester." (PMID 36483860, 2022). "Type 1 diabetes mellitus (T1D) corresponds to 90% of all diagnoses of diabetes in pediatric age and is defined as a chronic autoimmune disease due to an immune-mediated destruction of insulin-producing β-cells of the pancreas." (PMID 35420265, 2022). "In diabetes, impaired insulin signaling pathways lead to increased lipolysis and increased levels of FFAs in the body, resulting in increased utilization of FAs." (PMID 35509833, 2022). "The same DNA aptamer was used in another assay for insulin detection in serum samples from patients with diabetes." (PMID 35884911, 2022).